FAM110A (family with sequence similarity 110 member A)
Synonyms: C20orf55; bA371L19.3
Tractability: PROTAC: ubiquitination databases record sites on it.
Gene: Protein-coding gene on chromosome 20 (833,715 to 857,463, forward strand). Ensembl gene ENSG00000125898.
Subcellular location: Cytoplasm; Cytoplasm, cytoskeleton, microtubule organizing center, centrosome; Cytoplasm, cytoskeleton, spindle pole
Subcellular location (Human Protein Atlas): Nucleoplasm; Vesicles; Cytosol
Gene Ontology:
Molecular function: protein binding
Biological process: mitotic spindle organization
Cellular component: centrosome; cytosol; nucleus; spindle microtubule; spindle pole; cell cortex; cytoplasm
Genetic constraint (gnomAD): Loss-of-function variants: 9 observed, 9.86 expected, observed/expected ratio (o/e) 0.91, 90% interval 0.55 to 1.57. That is too few expected variants to judge how well the gene tolerates losing a copy. Missense variants: 436 observed, 379.18 expected, observed/expected ratio (o/e) 1.15, 90% interval 1.06 to 1.25. Synonymous variants: 217 observed, 175.77 expected, observed/expected ratio (o/e) 1.23, 90% interval 1.1 to 1.38.
Homologues: Orthologues: chimpanzee FAM110A (98% identical), macaque FAM110A (97% identical), dog FAM110A (91% identical), pig FAM110A (91% identical), guinea pig FAM110A (88% identical), rat Fam110a (86% identical), mouse Fam110a (86% identical), rabbit FAM110A (86% identical), tropical clawed frog FAM110A (36% identical). Paralogues in human: FAM110B (43% identical), FAM110C (29% identical), FAM110D (24% identical).
Diseases named in the same sentence as FAM110A in open-access papers:
FAM110A is named in the same sentence as 25 diseases in open-access papers, as found by Europe PMC text mining. Sharing a sentence is not in itself a finding about the gene and the disease. The quoted sentences say what the papers report.
pancreatic cancer (3 papers, 2022 to 2024). "It was previously found that family with sequence similarity 110 member A (FAM110A) participate in the regulation of the cell cycle and plays an oncogenic role in pancreatic cancer." (PMID 36923407, 2023). "FAM110A exerts an oncogenic role by facilitating malignant biological behaviors of pancreatic cancer cells." (PMID 36923407, 2023). "No staining was observed for FAM110A in normal pancreatic tissues, whereas moderate FAM110A staining was observed in ductal-like epithelial cells and surrounding mesenchymal-like cells in pancreatic cancer tissues." (PMID 35154458, 2022). "The goal of this study was to uncover the role and mechanism of FAM110A in pancreatic cancer." (PMID 35154458, 2022). "This suggests that FAM110A plays an important role in tumor growth and may serve as a prognostic marker and therapeutic target for pancreatic cancer." (PMID 35154458, 2022). "In conclusion, this is the first demonstration of the significance of FAM110A in pancreatic cancer." (PMID 35154458, 2022). "In addition, pancreatic cancer patients with high FAM110A expression showed significantly reduced overall survival." (PMID 35154458, 2022). "FAM110A may induce the occurrence and progression of pancreatic cancer." (PMID 38568089, 2024). "Quantitative PCR and Western blot of three pancreatic cancer cell lines (PANC-1, BXPC3 and ASPC1) and one pancreatic ductal epithelial cell line (HPDE6-C7) confirmed the elevated FAM110A expression levels in PDAC cells." (PMID 35154458, 2022). "This leads us to propose a new oncogenic TSPAN1/FAM110A/HIST1H2BK/G9a axis in PDAC that is involved in the modulation of tumor progression and represents a novel therapeutic approach for pancreatic cancer treatment." (PMID 35154458, 2022). "The elevated expression of FAM110A in PDAC was confirmed by Quantitative PCR and Western blot of 12 pairs of clinical pancreatic cancer tissues and adjacent normal tissues." (PMID 35154458, 2022). "Collectively, the newly identified TSPAN1/FAM110A/HIST1H2BK/G9a axis promotes PDAC progression and represents a novel therapeutic strategy against pancreatic cancer." (PMID 35154458, 2022). "Due to relatively greater differences in FAM110A expression between pancreatic cancer tumor and nontumor tissues than in other types of cancer, we focused on pancreatic cancer in this study." (PMID 35154458, 2022).
Hypertension (2 papers, 2018 to 2019). The presence of chronic increased pressure in the systemic arterial system. "FAM110A has been reported to be significantly associated with young-onset hypertension in Han Chinese population of Taiwan." (PMID 31561612, 2019). "The mechanism of FAM110A, PREP, ANKRD9, DCPS, WFDC12, TPTE, and LAMB2 genes on the occurrence and development of hypertension is not yet clear." (PMID 29379041, 2018).
pancreatic adenocarcinoma (2 papers, 2022 to 2023). "There was also a significant increase in FAM110A mRNA in pancreatic adenocarcinoma (PAAD) tissues (n=179) compared with adjacent nontumor tissues (n=171) according to the TCGA database." (PMID 35154458, 2022).
liver cancer (1 paper, 2023). An epithelial or non-epithelial malignant neoplasm that arises from the liver. "Moreover, our bioinformatic results show that FAM110A is associated with poor prognosis of liver cancer and immune response." (PMID 36923407, 2023).
posterior cortical atrophy (1 paper, 2020). Posterior Cortical Atrophy (PCA) is a rare progressive neurodegenerative disorder with a typical onset between 50-65 years of age characterized by progressive impairment of higher visual processing skills and other posterior cortical functions without any evidence of ocular abnormalities. "Variants in the FAM110A (rs1014897), the CNTNAP5 (rs76854344) and NTM (rs1040103) genes associated with this inflammatory module have been previously linked to posterior cortical atrophy, LOAD, and white blood cell count." (PMID 32492070, 2020).
skin cutaneous melanoma (1 paper, 2023). "In contrast, FAM110A expression in the tumor tissues of KICH and skin cutaneous melanoma (SKCM) was significantly decreased." (PMID 36923407, 2023).
cancer (4 papers, 2022 to 2025). A tumor composed of atypical neoplastic, often pleomorphic cells that invade other tissues. "Based on the findings, more studies are expected to reveal the underlying mechanism of FAM110A regulating tumor immune microenvironment in the future, which would be beneficial for progresses of cancer immunotherapy." (PMID 36923407, 2023). "The association of FAM110A with cancer patient prognosis, especially immunotherapy efficacy, requires further clinical validation." (PMID 36923407, 2023). "Based on our data, the three cancer types that showed the strongest association between FAM110A and the stroma score were PRAD, LGG, and KIRC." (PMID 36923407, 2023). "Our data suggested that FAM110A had the strongest positive correlation with these immune checkpoint genes in cancers where FAM110A is considered an important risk factor, such as LIHC and SKCM." (PMID 36923407, 2023). "To identify the potential association of FAM110A with cancer, we investigated the expression levels of FAM110A in different cancer tissues and their corresponding adjacent nontumor tissues according to available databases." (PMID 35154458, 2022). "FAM110A has been associated with cell cycle regulation, and its altered expression could affect cellular proliferation and apoptosis, critical processes in cancer development and progression." (PMID 39915534, 2025). "FAM110A affected prognosis and was associated with the expression of multiple immune checkpoint genes and abundance of tumor-infiltrating immune cells across multiple types of cancer, especially in liver hepatocellular carcinoma (LIHC)." (PMID 36923407, 2023). "This may explain the association between FAM110A overexpression and poor prognosis in patients with cancer." (PMID 36923407, 2023). "Our results showed that FAM110A mRNA is widely distributed and overexpressed in most cancer tissues compared to that in normal tissues." (PMID 36923407, 2023). "Our previous results revealed that FAM110A is closely related to patient prognosis and immunity in pan-cancer." (PMID 36923407, 2023). "To further elucidate the effect of FAM110A expression on the prognosis of patients with cancer, we downloaded TCGA RNA-seq and clinical data." (PMID 36923407, 2023). "In addition, we further explored FAM110A expression across different cancer pathological stages using the GEPIA database and found that FAM110A mRNA expression was correlated with clinicopathological stages in BRCA, LIHC, SKCM, and THCA." (PMID 36923407, 2023). "Here, we analyzed the association of FAM110A with more than 40 immune checkpoint genes in pan-cancer based on the TCGA database and verified the correlation of FAM110A between several immune checkpoint genes, including PD-1, PD-L1, LAG-3, and CTLA-4 in the TIMER 2.0 database." (PMID 36923407, 2023). "In this study, we employed a series of bioinformatics approaches to conduct pan-cancer analysis of FAM110A from multiple aspects, including gene expression and genomic alterations, correlation with prognosis, immunological markers, immune infiltration, and gene sets of interest." (PMID 36923407, 2023). "However, research on FAM110A, particularly regarding the relevance of immune responses in cancer, is currently inadequate." (PMID 36923407, 2023). "It would be interesting to evaluate the role of FAM110A in other cancers in the future." (PMID 35154458, 2022). "FAM110A may serve as a prognostic and immunological biomarker for human cancer." (PMID 36923407, 2023). "In view of the abnormal expression levels of FAM110A in tumors, the Kaplan–Meier method and COX regression analysis were conducted, and the results demonstrated that FAM110A may serve as a potential prognostic biomarker for a variety of cancers, especially LIHC." (PMID 36923407, 2023). "However, the prognostic value of FAM110A in pan-cancer and its involvement in immune response remain unclear." (PMID 36923407, 2023).
cancer (continued). "We used the TIMER database to explore the connection between FAM110A expression levels and the degree of tumor-infiltrating immune cell (TIIC) infiltration in pan-cancer." (PMID 36923407, 2023). "Our findings also demonstrated a significant correlation between FAM110A mRNA expression and CNV and methylation in pan-cancers." (PMID 36923407, 2023).
tumor (3 papers, 2022 to 2025). "The three tumor types that showed the strongest association between FAM110A expression and immune score were LAML, SKCM, and LIHC." (PMID 36923407, 2023). "To exclude the bias caused by non-tumor events, we further evaluated the effect of FAM110A expression levels on disease-specific survival (DSS)." (PMID 36923407, 2023). "CNV and methylation were associated with abnormal FAM110A mRNA expression in tumor tissues." (PMID 36923407, 2023). "A previous study found that FAM110A was expressed at significantly higher levels in tumor samples in LUSC than in control samples and was significantly correlated with the prognosis of LUSC patients." (PMID 39915534, 2025). "We utilized the ESTIMATE algorithm to calculate the stroma score, immune score, and estimate score of relevant tumor samples based on the TCGA database and assessed the correlation between FAM110A expression levels and those scores." (PMID 36923407, 2023). "We employed TIMER 2.0 website to explore the expression changes of FAM110A between tumor tissues and correspond normal tissues in the TCGA database." (PMID 36923407, 2023). "According to the IHC scoring criteria, the high expression rate of FAM110A in tumor tissues was 56.7% (68/120) and the low expression rate was 43.3% (52/120)." (PMID 36923407, 2023). "A significant positive correlation between FAM110A expression and tumor purity was found in BRCA-luminal, GBM, and LGG, while a significant negative correlation was found between KIRC and SKCM." (PMID 36923407, 2023). "Because of the contradictory roles played by FAM110A in prognosis and its association with immune checkpoints, we selected LIHC and BLCA as representative tumor types for subsequent analyses." (PMID 36923407, 2023). "We further investigated the link between FAM110A expression and tumor purity." (PMID 36923407, 2023). "Results from the TIMER 2.0 database revealed a significant positive correlation between FAM110A expression and the expression of CD8+ T cells, T cells (general), monocytes, tumor-associated macrophages, M2 macrophages, dendritic cells, T helper type 1 (Th1), and exhausted T cells in LIHC." (PMID 36923407, 2023). "FAM110A expression was elevated in most tumor tissues compared with that in normal tissues." (PMID 36923407, 2023). "As a result, we propose that FAM110A plays a delicate role in tumor initiation or development based on differential expression profiles and may affect immunotherapy efficacy to some extent." (PMID 36923407, 2023). "We found that the tumor-promoting capacity of FAM110A could be markedly abolished by HIST1H2BK knockdown in PDAC." (PMID 35154458, 2022). "Furthermore, elevated FAM110A expression enhanced tumor growth in subcutaneous transplantation models in nude mice." (PMID 35154458, 2022). "The tumor-promoting capacity of TSPAN1 was markedly abolished by FAM110A knockdown." (PMID 35154458, 2022). "RNA-Seq, Western blot and luciferase-reporter assays were used to explore mechanism of FAM110A action in PDAC, and the involved pathway was verified by tumor phenotypic rescue experiments." (PMID 35154458, 2022). "Our results revealed that FAM110A protein expression was significantly increased in tumor tissues compared to that in matched non-tumor adjacent tissues, the subcellular localization of FAM110A was in the nucleoplasm and cytoplasm." (PMID 36923407, 2023).
FAM110A also shares sentences with these, for which no sentence is quoted: prostate carcinoma (2 papers); acute myeloid leukemia (1); adrenocortical carcinoma (1); breast carcinoma (1); diffuse large B-cell lymphoma (1); mastitis (1); mesothelioma (1); myelofibrosis (1); Onset (1); ovarian serous cystadenocarcinoma (1); prostate (1); sarcoma (1); testicular germ cell tumor (1); thymoma (1); type 2 diabetes (1); uterine carcinosarcoma (1); uveal melanoma (1).